RN7SL204P (RNA, 7SL, cytoplasmic 204, pseudogene)
Gene: Miscellaneous RNA gene on chromosome 2 (236,072,295 to 236,072,556, forward strand). Ensembl gene ENSG00000264676.
Homologues: Orthologues: macaque Metazoa_SRP (43% identical). Paralogues in human: RN7SL470P (64% identical), RN7SL510P (63% identical), Metazoa_SRP (63% identical), RN7SL202P (63% identical), RN7SL391P (63% identical), RN7SL596P (63% identical), Metazoa_SRP (62% identical), RN7SL96P (62% identical), Metazoa_SRP (61% identical), RN7SL774P (60% identical), RN7SL274P (60% identical), Metazoa_SRP (60% identical), and 700 more.